TWIST1 (twist family bHLH transcription factor 1)
Diseases named in the same sentence as TWIST1 in open-access papers (continued):
Sharing a sentence is not in itself a finding about the gene and the disease.
cancer (continued). "Ligand-independent activation of ephrin receptor EPHA2 by matrix stiffening leads to LYN kinase-mediated Twist1 phosphorylation and nuclear translocation, thereby promoting EMT, cancer cells invasion and metastasis." (PMID 35331296, 2022). "From the lncRNA-mRNA pathway network, PYCARD, RIPK2, and CASP1 were found to be significantly enriched in the NOD-like receptor signaling pathway, whereas MAP2K2, LUM, RPS6, PDCD4, TWIST1, and HIF1A were significantly enriched in proteoglycans in cancers." (PMID 36619896, 2022). "Related studies, using a mouse model of spontaneous squamous cell carcinoma, demonstrated that cancer cells undergo EMT and spread to the circulation, which is facilitated by activation of the EMT-inducible transcription factor TWIST1." (PMID 36076302, 2022). "As a carcinoma inhibitor gene, RBM24 regulates Twist1 to achieve LN metastasis and EMT suppression in HSCC." (PMID 36213838, 2022). "We also found strong correlations between MES and ADRN TFs with markers of cancer cell stemness and cancer cell motility including CDH1, CDH2, NANOG, SOX2, TWIST1, VIMENTIN, and Fibronectin across cancers." (PMID 35201514, 2021). "The results of the study showed us the TNF-α/NF-κB/Twist1 signaling pathway was related to apoptosis, invasion, metastasis and EMT in cancer cells." (PMID 33854637, 2021). "Twist1 is a master transcription factor that induces migration and invasion and promotes EMT in various cancer cells." (PMID 34249678, 2021). "In numerous cancer cell lines, EMT and cancer stem cell properties have been induced through the overexpression of transcription factors, such as the Twist1, Snail, Zeb, and FoxC families." (PMID 34577566, 2021). "Both Twist1 and Twist2 function in the transcriptional regulation of developmental processes, but Twist1 is better studied and is a known activator of EMT in cancer cells." (PMID 33626096, 2021). "Particularly, concurrent overexpression of the oncogenic genes Twist1, Snail1, and Notch1 strongly induces EMT and enhances stemness, thereby inducing cancer and metastasis." (PMID 34922602, 2021). "Although previous studies have suggested multiple roles for HK2 in cancer cell chemoresistance, we demonstrated that HK2 mediates oxaliplatin resistance by stabilizing Twist1." (PMID 34378321, 2021). "Twist1 functions as a transcription factor to drive the transcription of numerous oncogenic genes, and the overexpression of Twist1 triggers EMT and cancer metastasis." (PMID 34922602, 2021). "It has been disclosed that POU2F1 promoted EMT by targeting TWIST1 and SLUG, which are part of a group of TFs inducing EMT in cancer cells, therefore facilitating the invasion and metastasis of cancer cells." (PMID 34257651, 2021). "EMT-TFs belonging to the ZEB (ZEB1 and ZEB2), SNAIL (SNAIL1 and SNAIL2/SLUG), and TWIST (TWIST1 and TWIST2) families are best-studied in the context of cancer." (PMID 34638349, 2021). "Since EMT has been shown to be comprehensively involved in GCB resistance in several cancer types, subsequent comparisons were carried out among major transcription factors of EMT (EMT-TFs), including Snail, Slug, Twist1 and ZEB2." (PMID 33922395, 2021). "Accordingly, TWIST1 enhances epithelial-to-mesenchymal transition (EMT) and promotes the formation of cancer stem cells (CSCs)." (PMID 33752711, 2021). "Protein enrichment involved with cancer stem cell signaling, EMT, and inflammatory process were identified as cores for cancer invasion and metastatic process related with TWIST1 and CSF1 overexpression." (PMID 33466385, 2021).
cancer (continued). "Twist1 is a key transcription factor that promotes the EMT, which leads to cell migration, invasion, cancer metastasis, and therapeutic resistance." (PMID 33626096, 2021). "Mesenchymal transcriptional factors such as Snail1 and Twist1 promote CSC-like phenotypes, resulting in resistance to treatment, cancer recurrence, and metastasis." (PMID 33890571, 2021). "The KEGG pathway enrichment for the TWIST1-correlated genes suggests enrichment of the PI3K-AKT signalling pathway, proteoglycans in cancer, RAS signalling pathway and focal adhesion." (PMID 33299129, 2021). "SLUG and TWIST1, master EMT-inducing transcription factors, made essential contributions to TMPRSS4-mediated cancer stem cell (CSC) features through upregulation of SOX2." (PMID 34809669, 2021). "Twist1 is a master EMT-inducing gene and plays a critical role in cancer metastasis in various malignant tumors." (PMID 34922602, 2021). "Several other CSC biomarkers & effectors, such as TWIST1, ALDH, EpCAM, glucose, and transporters (GLUTs), were also used as CSC targets for cancer therapy, which largely depend on the specific cancer types." (PMID 34959397, 2021). "TWIST1 is a transcription factor that plays an important role in driving the process of epithelial mesenchymal transition (EMT) during development and in cancer." (PMID 34277708, 2021). "For restoring sensitivity to cancer therapies, the appropriate approaches regulating EMT-TFs, including Snail, Twist1, and ZEB1, are required." (PMID 33768509, 2021). "Twist1 is reported to function as an essential transcription factor that regulates the EMT process, and eventually contributes to cancer metastasis." (PMID 33768509, 2021). "We showed that LIMK2 stabilizes TWIST1 by direct phosphorylation at four sites, which leads to EMT and cancer stem cell phenotypes in CRPC." (PMID 34066036, 2021). "Specifically, TWIST1 and MMP7 are known to be involved in epithelial‐mesenchymal transition (EMT), a key process in cancer progression." (PMID 34562306, 2021). "In cancer cells, ZFP36 is believed to act as an EMT suppressor by binding to AU-rich elements in the mRNA 3′UTRs of Twist1 and Snail1." (PMID 34238924, 2021). "This up-regulation of RPS16 promotes the growth and migration of HCC cells by promoting the expression of Twist1 and Snail, thereby revealing the new pathological function of RPS16 in cancer." (PMID 34154657, 2021). "Our data indicate that triptonide is a novel, potent Twist1 protein inhibitor, warranting further development of Twist1-targeted drugs for the treatment of TNBC and other types of cancer with aberrant overexpression of Twist1." (PMID 34922602, 2021). "Low expression of Per2 led to the activation of EMT genes TWIST1 and SLUG and promoted cancer metastasis." (PMID 32437452, 2020). "We also evaluated the effects of FOXQ1 expression on Twist1, which has been established as a direct target of FOXQ1 in cancers including CRC." (PMID 33330033, 2020). "Both MYC and Twist1 demonstrated binding at multiple sites in the promoter regions of CCL2 and IL13 in the ChIP-seq data from several different cancer cell lines." (PMID 31933479, 2020). "Further, combined MYC and TWIST1 expression correlated strongly with CCL2 and IL13 in the pan-cancer cohort (p=1.4×10−109)." (PMID 31933479, 2020). "For example, the VGF nerve growth factor inducible (VGF) plays a role in cell plasticity and induces transcription factor TWIST1, which facilitates EMT in cancer cells." (PMID 33225905, 2020). "Further, in 33 human cancers (n = 9502) MYC and TWIST1 predict poor survival (p=4.3×10−10), CCL2/IL13 expression (p<10−109) and TAM infiltration (p<10−96)." (PMID 31933479, 2020).
cancer (continued). "It is well reported that TWIST-1 is considered as the main regulator of EMT and is up-regulated in a large number of malignant tumors determining the onset of the metastatic process, via promoting invasiveness in both spontaneous and experimental models." (PMID 33297475, 2020). "This revealed that patients that had higher levels of MYC and TWIST1 proteins in their tumors also had increased levels of CCL2 and IL13, more activated macrophages and were less likely to recover from their cancer." (PMID 31933479, 2020). "First, in 9502 patients with 33 different types of human cancer, the subset of tumors with MYC and TWIST1 predicts poor survival, CCL2/IL13 expression and TAM infiltration." (PMID 31933479, 2020). "Zeb1, Twist1, Snail, Slug, or treatment with TGF-β promote both tumorigenicity and stemness of cancer cells." (PMID 33297508, 2020). "FOXQ1 is an established modulator of Twist1 expression and a regulator of cancer invasion and metastasis in CRC, and the role of Twist1-induced CCL2 in angiogenesis has been previously demonstrated." (PMID 33330033, 2020). "This analysis suggested the hypermethylation of TWIST1, CDKN2A (ARF2), PIK3R5 and TBX2 are present in cancers of the breast, colon, lung and prostate." (PMID 33143142, 2020). "Ectopic ISX expression enhances EMT marker expression, including TWIST1, Snail1, and VEGF, induces cancer metastasis, but suppresses E‐cadherin expression." (PMID 31908141, 2020). "TWIST1 and ADAM22 were also positively correlated with cancer stage, while GAL was an independent OS predictor in addition to MYCN and age." (PMID 32629858, 2020). "Recent data also provides evidence that the polycomb group protein, Bmi-1, is a downstream target of Twist1 and a key regulator of EMT and cancer metastasis." (PMID 32153503, 2020). "Given the important role that TWIST1 plays in EMT, cancer outcomes, and response to chemotherapeutic agents, a fuller understanding of the interaction of HPV16 with TWIST1 is warranted." (PMID 33298572, 2020). "IHC results showed that the expression of FOXQ1, Twist1, and CCL2 in CRC tissues was significantly higher than that in para-carcinoma tissues." (PMID 33330033, 2020). "Increased TWIST1 expression promotes EMT by regulating cell motility and invasive activity and enhances some features of cancer stem cells through control of downstream gene expression." (PMID 30154425, 2019). "Previous studies have confirmed that Twist1, Snail1 and Zeb1 were the critical transcriptional factors regulating EMT of cancer cells." (PMID 30755243, 2019). "TWIST1 is a transcription factor that is involved in the epithelial-to-mesenchymal transition (EMT) pathway and it is frequently overexpressed in cancer." (PMID 30909364, 2019). "Aberrant Twist1 overexpression facilitates EMT, cell motility, and invasive activity, and enhances some features of cancer stem cells via control of downstream gene expression." (PMID 31383001, 2019). "TWIST1 has previously been shown to promote EMT and a cancer stem-like cell (CSLC) phenotype by transcriptional activation of mesenchymal markers and CSLC-associated proteins in HeLa." (PMID 31888045, 2019). "TWIST1, a transcription factor with a basic helix loop helix domain, plays important roles in EMT and cancer metastasis." (PMID 30548372, 2019). "Prior to conducting the biological study of TWIST1 ceRNET in LUAD in vitro, we first evaluated the expression profile of TWIST1 in LUAD cancer cell lines by RT-PCR analysis." (PMID 31645542, 2019). "TWIST1, SNAI2 and FOXC2 also showed moderate inverse correlations with immune cell content in four of five cancer types." (PMID 31780722, 2019). "Twist1 upregulation or activation is involved in EMT, metastasis, angiogenesis, and is responsible for the “stemness” of cancer cells and the generation of drug resistance, gaining significance in cancer therapeutics." (PMID 29849945, 2018).
cancer (continued). "In our study, among the selected genes related to the partial processes of cancer cell invasivity, we identified higher cancer-specific methylation levels in the CXCL12, TWIST1 and SNAI2 genes." (PMID 30189837, 2018). "Based on these observations, we propose a model of the molecular pathways involving EMT, including Twist1‐Rac signal axis and Snail, to regulate cellular migratory and invasion capability and intracellular stiffness in EMT in cancer metastasis." (PMID 29726584, 2018). "Twist1, considered as a master regulator of EMT and metastasis, is expressed in a variety of cancers." (PMID 29950484, 2018). "First, we examined coexpression of key component of the PFL; Twist1, Prrx1, and TNC in clinical samples such as patient tissue-derived ex vivo cultured CAFs, archived paraffin-embedded cancer tissues, and TCGA data." (PMID 30069061, 2018). "A recent study has also found that promoter-specific hypomethylation induces the ectopic expression of the cancer-related genes PLS3, GATA6 and TWIST1 in SS." (PMID 30701021, 2018). "Cancer markers previously used to detect MRD are predominantly methylated in epithelial and intermediate cell lines, with RASSF1A, TWIST1, and RARβ methylation covering more of the epithelial–mesenchymal spectrum in the cell line panel." (PMID 30154364, 2018). "To gauge the role of Twist1 downstream of AMPK in the process of EMT, we investigated the effects of Twist1 depletion in AMPK-mediated EMT response of cancer cells." (PMID 29950484, 2018). "On the other hand, both qPCR and western blot assays confirmed that NKILA suppressed activation of several NF-κB target genes including CCND1, TWIST1, MMP9 and XIAP, all of which play vital roles in cancer growth and metastasis." (PMID 29348395, 2018). "This factor is widely expressed in human cells and shown to promote cancer metastasis through enhancing translation of hypoxia-inducible factor-1α (HIF-1α) and TWIST (Twist family bHLH transcription factor 1)." (PMID 29439529, 2018). "POU2F1 induced the transcription of Twist1, Snai1, Snai2 and ZEB1 genes which induce cancer cell EMT." (PMID 28489585, 2017). "Collectively, these findings showed that POU2F1 induced the transcription of Twist1, Snai1, Snai2 and ZEB1 genes which induce cancer cell EMT." (PMID 28489585, 2017). "As a bHLH transcription factor, TWIST1 effectively plays a role in EMT, with a controlling function in the migration, invasion and metastasis of cancer cells." (PMID 29299035, 2017). "The transcription factor TWIST1 plays an important role in the epithelial–mesenchymal transition (EMT) process and in the migration, invasion and metastasis of cancer cells." (PMID 29299035, 2017). "This also led us to infer that although prominently known to be one of the key promoters of EMT and invasiveness in a number of cancer types, the role of SOX2-dependent TWIST1 in maintaining stemness was more prominent when SOX2 expression was high in brCSCs." (PMID 28835684, 2017). "A series of transcription factors have been reported to promote EMT process in cancer metastasis, including SNAL1, TWIST1, ZEB1, and SIP1 (ZEB2)." (PMID 28423728, 2017). "Twist1, a basic helix-loop-helix transcription factor, has been demonstrated as an important EMT marker in many cancers." (PMID 29262637, 2017). "Depletion of Twist1 in ex vivo cultured ESCC CAFs induced significant decrease in migration, invasion, colony formation, sphere formation, and contractibility of ESCC cancer cells compared to control CAFs." (PMID 29029429, 2017). "The results demonstrated that Twist1, a central protein in EMT, affects intravascular migration of arrested cancer cells, remodels the vasculature, and promotes cancer cell exit from the blood circulation through a β1 integrin-independent mechanism." (PMID 28955335, 2017). "The six selected genes (TWIST1, LAMB1, THY1, EZH2, SALL4, and TCF3) are involved in cell differentiation, HCC cancer stem cells (CSCs) markers, and CSCs involved pathways." (PMID 28158312, 2017).
cancer (continued). "TTP bound to the AU-rich element (ARE) within the mRNA 3′UTRs of Twist1 and Snail1, enhanced the decay of their mRNAs and inhibited the EMT of cancer cells." (PMID 26840564, 2016). "Since the levels of TRIM28 and TWIST1 are positively correlated in cancer tissues and overexpression of TRIM28 enhances both cell migration and invasion, we want to further determine if TRIM28 functions through TWIST1." (PMID 27412325, 2016). "A group of transcription factors have been demonstrated to be capable of orchestrating EMT program in cancer progression, such as Snail (SNAI1), Slug (SNAI2), ZEB2 (SIP1), ZEB1 and Twist1." (PMID 27121312, 2016). "Twist1 plays a crucial role in epithelial-mesenchymal transition (EMT), metastasis, and cancer stemness through direct regulation of BMI1." (PMID 26823670, 2016). "Induced expression of EMT factor Twist1 in mammary epithelial cells can generate EMT and stemness, thus linking EMT to cancer CSCs." (PMID 27335684, 2016). "Our data propose a new model whereby TTP down-regulates Twist1 and Snail1 and inhibits both the EMT and the proliferation of cancer cells." (PMID 26840564, 2016). "The regulation of EMT genes, such as SNAIL, SLUG, and TWIST1, promotes an EMT phenotype, which can initiate the metastasis and dedifferentiation of cancer cells into CSCs." (PMID 28116318, 2016). "Many bHLH transcription factors, such as Twist1, TCF4, DEC1, have been reported to act as strong promoters of EMT and metastatic spread in many human carcinomas." (PMID 27384482, 2016). "TWIST1 and TWIST2 share many functions, such as their regulation of hematological malignancies and their role in cancer progression and metastasis." (PMID 25895023, 2015). "Collectively, the present study demonstrates a mechanical cascade of BRMS1 suppressing cancer cell invasion through downregulating HIF-1α transcript and consequently reducing Snail and TWIST1 expression." (PMID 26520789, 2015). "Selective iNOS (1400 W) and pan-NOS (L-NMMA and L-NAME) inhibitors diminished cell proliferation, cancer stem cell self-renewal, and cell migration in vitro, together with inhibition of EMT transcription factors (Snail, Slug, Twist1, and Zeb1)." (PMID 25849745, 2015). "A direct link between EMT and cancer stem cells was demonstrated by findings that EMT activators, such as Twist1, can induce both EMT and stemness." (PMID 26091803, 2015). "Many signals generated within the cancer microenvironment activate transcription factors considered to be promoters of EMT, such as SNAIL1, TWIST1 and ZEB1." (PMID 26362312, 2015). "Therefore, antagonists against TWIST1 may hold further promise for cancer therapeutics." (PMID 26359363, 2015). "TWIST1 has been shown to play an important role in the process of Epithelial Mesenchymal Transition (EMT), which correlates with higher cancer aggressiveness and poor survival rates." (PMID 25238494, 2014). "Hypoxia induces an EMT-like phenotype in cancer cells, and HIF-1α regulates the expression of Twist1 by binding directly to the hypoxia-response element (HRE) in the proximal promoter of Twist1." (PMID 25200065, 2014). "This study focuses on identifying and comparing Twist1 genomic occupancy in developing ECC, limb buds, and a cancer cell line." (PMID 25262113, 2014). "RREB1 is expressed in developing tissues and cancer where it acts downstream of Ras and MAPK signaling Twist1 is required for K-Ras mediated progression of lung tumors, supporting a role for RREB1 in this regulatory interaction." (PMID 25262113, 2014). "An earlier study suggests that Ras also induces the expression of other EMT inducer such as Twist1 and SOX4 in cancer cells." (PMID 24721839, 2014).